SERHL2 (serine hydrolase like 2)
Description:
Probable serine hydrolase. May be related to cell muscle hypertrophy.
Synonyms: dJ222E13.1
Tractability: PROTAC: ubiquitination databases record sites on it.
Gene: Protein-coding gene on chromosome 22 (42,553,617 to 42,574,387, forward strand). Ensembl gene ENSG00000183569.
Subcellular location: Cytoplasm, perinuclear region; Peroxisome
Gene Ontology:
Cellular component: cytoplasmic vesicle; perinuclear region of cytoplasm; peroxisome
Genetic constraint (gnomAD): Loss-of-function variants: 23 observed, 15.56 expected, observed/expected ratio (o/e) 1.48, 90% interval 1.05 to 1.9. The upper end of that interval is the gene's LOEUF score, 1.9, which puts it in group 6 of 6, group 1 being the genes least tolerant of losing a copy. Missense variants: 216 observed, 171.01 expected, observed/expected ratio (o/e) 1.26, 90% interval 1.13 to 1.41. Synonymous variants: 86 observed, 66.16 expected, observed/expected ratio (o/e) 1.3, 90% interval 1.09 to 1.55.
Homologues: Orthologues: dog SERHL2 (66% identical), mouse Serhl (65% identical), rat Serhl2 (64% identical), pig SERHL2 (63% identical), tropical clawed frog serhl.2 (43% identical), tropical clawed frog serhl (40% identical), zebrafish serhl (38% identical), Drosophila melanogaster CG7632 (30% identical), Drosophila melanogaster CG15820 (29% identical), Drosophila melanogaster CG5704 (28% identical), Drosophila melanogaster CG11309 (27% identical), Drosophila melanogaster CG15879 (27% identical), and 8 more. Paralogues in human: ABHD6 (19% identical), EPHX2 (19% identical), EPHX3 (18% identical), EPHX4 (18% identical), ABHD8 (17% identical), ABHD11 (15% identical), ABHD5 (14% identical), BPHL (14% identical), MEST (14% identical), ABHD4 (12% identical), ABHD14A (11% identical), ABHD14B (10% identical).
Diseases named in the same sentence as SERHL2 in open-access papers:
SERHL2 is named in the same sentence as 4 diseases in open-access papers, as found by Europe PMC text mining. Sharing a sentence is not in itself a finding about the gene and the disease. The quoted sentences say what the papers report.
atherosclerosis (1 paper, 2020). A disease characterized by the build-up of fatty material and calcium deposition in the arterial wall resulting in partial or complete occlusion of the arterial lumen. "Further studies are required to investigate the changes in promoter methylation in NETO1, FANK1, and SERHL2 in the development of atherosclerosis." (PMID 32398127, 2020).
type 2 diabetes (1 paper, 2025). "Furthermore, SERHL2 expression was increased in skeletal muscle of people with type 2 diabetes following a 52-week extensive exercise training intervention (GSE19420)." (PMID 39657853, 2025). "Additionally, in an exercise-in-a-dish model of cultured L6 myotubes, as well as in people with either normal glucose tolerance or type 2 diabetes, skeletal muscle SERHL2 mRNA was increased with long time EPS or endurance training, respectively." (PMID 39657853, 2025).
cancer (1 paper, 2024). A tumor composed of atypical neoplastic, often pleomorphic cells that invade other tissues. "However, from the literature, the present study is the first to document the association of SERHL2 with cancer hypoxia." (PMID 39660488, 2024).
tumours (1 paper, 2024). "Two genes were upregulated (SERHL2 and SPNS2) in low cytoplasmic CAIX tumours, while one gene (PCSK1N) was downregulated, as shown in the volcano plot and MA plot (respectively)." (PMID 39660488, 2024).